PPARA (peroxisome proliferator activated receptor alpha)
Diseases named in the same sentence as PPARA in open-access papers (continued):
Sharing a sentence is not in itself a finding about the gene and the disease.
Hypercholesterolemia (34 papers, 2011 to 2025). An increased concentration of cholesterol in the blood. "On the other hand, fenofibrate, which is a PPARα agonist (i.e., activates PPARα), is used for hypercholesterolemia, and was reported to inhibit cancer cell proliferation by increasing β-oxidation and inhibiting glycolysis." (PMID 33466690, 2021). "Specifically, our data shows that NR1C1 (PPARα) is among the downregulated genes in familial hypercholesterolemia." (PMID 29065888, 2017). "In this sense, we observed an increase in plasma cholesterol levels which are linked to the reduced expression of PPARA, and we observed significant differences in its expression in patients with hypercholesterolemia compared to those patients who do not present this comorbidity." (PMID 35052814, 2022). "Recently, in a hepatocyte-specific PPARα knockout mouse model an impaired liver and whole-body fatty acid homeostasis was observed, resulting in hepatic lipid accumulation (NAFLD) and hypercholesterolemia during aging." (PMID 27347932, 2016). "Hence, a deficiency of 20-HETE may reduce the hypolipidemic effects of PPARα, leading to decreased HDL-C and hypercholesterolemia." (PMID 29484037, 2018). "A recent study shows that statins, usually used for the treatment of hypercholesterolemia, increase the expression of neurotrophins in the brain; this result is due to the binding to a particular domain of PPARα, which is independent of the pathway typical of mevalonate." (PMID 27347932, 2016). "Thus, additional amelioration of HFD-induced hypercholesterolemia by the CFE might be achieved, at least in part, through activation of PPARα." (PMID 24265809, 2013).
inflammatory bowel disease (34 papers, 2010 to 2025). A spectrum of small and large bowel inflammatory diseases of unknown etiology. "It inhibits apoptosis and inflammatory bowel disease (IBD) in the mouse colonic epithelial cell line M064 through PPARα inactivation." (PMID 39875357, 2025). "Atorvastatin may be beneficial in treating inflammatory bowel disease by affecting the PPARα pathway." (PMID 39451206, 2024). "A Boolean network explorer (BoNE) computational algorithm was used to identify a dual agonist of the nuclear receptors PPARα and PPARγ that may be therapeutic in treating inflammatory bowel disease." (PMID 35288651, 2022). "Due to its anti-inflammatory and metabolic functions, PPARα is regarded as a valuable therapeutic target in chronic colitis in its various forms, such as inflammatory bowel disease (IBD): ulcerative colitis or Crohn disease (CD)." (PMID 36430628, 2022). "Here we used BoNE to query an Inflammatory Bowel Disease (IBD)-map and prioritize a therapeutic strategy that involves dual agonism of two nuclear receptors, PPARα/γ." (PMID 35288651, 2022).
lung cancer (33 papers, 2007 to 2025). A malignant neoplasm involving the lung. "PPARα has been implicated in hepatocellular carcinoma inrodents, whereas activation of PAPRβ/δ promotes human lung carcinoma cell proliferation throughPI3-Kinase/Akt activation." (PMID 18704200, 2008). "When PPARα activity is therapeutically induced with fenofibrate, a clinically approved PPARα agonist, the deleterious changes in hepatic fatty acid metabolism are reversed, blood ketone levels rise, and cachexia is prevented in mice with lung cancer." (PMID 35719965, 2022). "The expressions of C/EBPα and PPARγ were upregulated in several cell lines, and SREPB1, HIF-1α, PPARα, and PPARβ were more widely overexpressed in lung cancer cells." (PMID 36293388, 2022). "In support of this concept, we previously reported decreased levels of beta hydroxybutyrate in mice with lung cancer induced cachexia, and significant anti-cachectic benefits when ketogenesis was restored with the PPARα agonist, fenofibrate." (PMID 35719965, 2022). "We have previously found that cachectic mice with lung cancer have reduced serum ketone body levels due to low PPARα activity in the liver." (PMID 35719965, 2022). "Previously, we found that mice with lung cancer induced cachexia have decreased PPARα activity in the liver." (PMID 35719965, 2022). "Here, we described PPARα-independent/ROS-dependent inhibitory effects of 25 μM FF on intercellular signaling between endothelium and lung cancer cells during their diapedesis." (PMID 30274176, 2018). "The involvement of PPARα in lung cancer biology has been extensively investigated within the past decade." (PMID 28316613, 2017). "In the context of lung cancer, with general agreement on its role as a tumor suppressor, the biological effects of activated PPARγ are perhaps better defined than those of PPARα or PPARβ/δ." (PMID 28316613, 2017). "Three PPARs, PPARα, PPARβ/δ, and PPARγ, display distinct biological activities and varied influences on lung cancer biology." (PMID 28316613, 2017). "In summary, increasing ketone body availability and hepatic PPARα activity through a ketogenic diet or ketone ester supplementation in mice with lung cancer did not increase survival, nor did it improve the maintenance of body weight and muscle mass." (PMID 35719965, 2022). "This might help in establishing tumor markers for lung cancer based on the level of endogenous PPAR ligands and the activities of PPARγ or PPARα." (PMID 35631448, 2022). "Unlike PPARγ agonists, however, the clinical applicability of PPARα and PPARβ/δ ligands in lung cancer has not been assessed." (PMID 28316613, 2017). "In one study, human lung cancer cell lines were shown to express PPARγ but not PPARα." (PMID 35631448, 2022).
myocardial infarction (33 papers, 2005 to 2026). Gross necrosis of the myocardium, as a result of interruption of the blood supply to the area, as in coronary thrombosis. "Polymorphisms in PPARA gene have been demonstrated to substantially affect the oxidative stress, lipid metabolism, progression of coronary atherosclerosis, and the risk of myocardial infarction." (PMID 37292135, 2023). "Two comparative studies linked single-nucleotide polymorphisms (SNPs) concerning PPARα in humans to a higher risk of myocardial infarction." (PMID 33322384, 2020). "Some studies found that chronic activation of PPARα is detrimental to cardiac recovery after ischemia and PPARγ activator was associated with increased mortality post-myocardial infarction in rats." (PMID 27955667, 2016). "A risk nomogram was established by ACSL1, ALDH2, CYP27A1 and PPARA, demonstrating a good ability for DCM and myocardial infarction prediction." (PMID 37056578, 2023). "Most animal studies applying ischemia/reperfusion or myocardial infarction procedures reported beneficial effects of PPARα agonists reflected by reduced infarct sizes and improved cardiac function." (PMID 36768666, 2023). "Later, first experimental studies investigating the effects of PPARα modulation on the outcome of myocardial infarction emerged." (PMID 33322384, 2020). "In rats with myocardial infarction, the dual PPARα/γ agonist TZD18 improved left ventricular function and increased the expression of enzymes related to myocardial energy metabolism and the content of high energy phosphate in mitochondria." (PMID 33322384, 2020). "Cardioprotective functions of PPARα were also proposed in a recent publication where the potential therapeutic effects of ginsenoide Rb-3 (GRb-3) on the outcome after myocardial infarction in mice were examined." (PMID 33322384, 2020). "This experiment was designed to assess the effects of testosterone replacement on the cardiac metabolic remodeling via regulating the expression of PPARα and its downstream genes in a castrated rat myocardial infarction model." (PMID 27413362, 2016). "In summary, administration of PPARα agonist WY-14643 mitigated the extent of myocardial infarction and incidence of reperfusion-induced arrhythmia." (PMID 26770648, 2016). "Taken together, these results suggested that endogenous testosterone deprivation impaired PPARα signaling in a rat model of myocardial infarction, and this effect was reversed by testosterone replacement." (PMID 27413362, 2016). "In conclusion, administration of PPARα agonist WY-14643 decreased the degree of myocardial infarction and incidence of reperfusion-induced arrhythmia." (PMID 26770648, 2016). "In the current study, administration of WY-14643, a PPARα agonist, reduced myocardial infarct size following ischemia-reperfusion injury in rats." (PMID 26770648, 2016). "Taken together, our findings suggest that testosterone can modulate myocardial metabolic remodeling by upregulating PPARα after myocardial infarction, exerting a protective effect on cardiac function." (PMID 27413362, 2016). "We took advantage of an experiment of nature, a common pair of SNPs that alter PPARA promoter activity, to demonstrate that PPARA expression level helps determine outcome after myocardial infarction and unstable angina in human subjects with DM." (PMID 20838448, 2010). "PPARα activation reduced myocardial infarct size and improved post-ischemic contractile recovery." (PMID 36142371, 2022). "The role of PPARα in myocardial infarction remains unclear as both beneficial and detrimental effects of PPARα activation have been reported." (PMID 33322384, 2020). "PPAR Research would like to express concern with the article titled “Testosterone Replacement Modulates Cardiac Metabolic Remodeling after Myocardial Infarction by Upregulating PPARα” published in PPAR Research in June 2016 due to flaws found in the quality of the article." (PMID 31308846, 2019).
myocardial infarction (continued). "Ligands of PPARγ and PPARα have been demonstrated to reduce myocardial infarct size in I/R; therefore, PPAR agonists may be useful in conditions associated with I/R injury of the heart and other organs." (PMID 30800167, 2019). "In the present study, real-time PCR and Western blotting showed that PPARα was downregulated at the mRNA and protein levels in the S-Cas group compared with the control group (P < 0.01), indicating that myocardial infarction-induced metabolic remodeling involved the suppression of PPARα signaling." (PMID 27413362, 2016). "Prospective model of PPARA variants and non-fatal myocardial infarction risk in the Go-DARTs cohort." (PMID 16309557, 2005). "It has been previously demonstrated that two common variants at the PPARA locus are associated with opposing risks of development of atherosclerotic vascular disease and myocardial infarction in two separate populations of non-diabetic male subjects taking part in the LOCAT and NPHS2 studies." (PMID 16309557, 2005). "In 2002, the group of C. Thiemermann was the first to examine the effects of PPARα agonists (clofibrate and WY14643) after experimentally induced myocardial infarction." (PMID 33322384, 2020). "The combination of the PPARα agonist fenofibrate and simvastatin did not reduce the overall rate of fatal cardiovascular events, nonfatal myocardial infarction, or nonfatal stroke as compared with simvastatin alone." (PMID 36768666, 2023). "Similar findings were observed in non-diabetic rats submitted to myocardial infarction and treated with the PPARα agonist clofibrate." (PMID 33322384, 2020). "Combination of the PPARα agonist fenofibrate and simvastatin did not reduce the rate of fatal cardiovascular events, nonfatal myocardial infarction, or nonfatal stroke, as compared with simvastatin alone." (PMID 33322384, 2020).
cholestasis (32 papers, 2007 to 2025). Impairment of the bile flow caused by obstruction within the liver, or outside the liver in the bile duct system. "Previous studies showed that activation of PPARα alleviates cholestasis injury caused by α-naphthylisothiocyanate (ANIT)." (PMID 34776958, 2021). "The anti-inflammation response associated with activated PPARα is decreased in cholestasis." (PMID 35370715, 2022). "Agonists of PPARα such as fibrates, act as adjunctive therapies that can mitigate cholestasis-related diseases by modulating bile acid synthesis, transport, and other processes." (PMID 40956833, 2025). "PPARα is involved in the regulation of bile acid metabolism, and the PPARα-null mice demonstrated more aggressive toxic effects of ANIT-induced cholestasis compared to wild-type mice, indicating a protective potential of basal PPARα." (PMID 40863335, 2025). "In contrast, administration of Uro-B significantly restored both protein and gene expression levels of hepatic PPARα, suppressing cholestasis-mediated liver injury." (PMID 40863335, 2025). "Recently, PPARα has been reported as a new therapeutic target to control the synthesis and transport of bile acids and inflammatory response during cholestasis, reducing cholestatic liver damage." (PMID 40863335, 2025). "In regard to cholestasis, elafibranor activates PPARα which inhibits CYP7A1 expression leading to a reduction in BAs synthesis, whereas the induction of CYP3A4, SULT2A1 and UGT2B4, and the expression of BSEP and MRP2, decrease BAs output and toxicity." (PMID 37371808, 2023). "In this review, we provide an overview of the function of peroxisome proliferator-activated receptor alpha (PPARα) and its adaptive response to cholestasis." (PMID 35924060, 2022). "Synthetic PPARα agonists have been identified, including fenofibrate, which is one of the most commonly used fibrates in cholestasis treatment trials; WY-14643; and bezafibrate, which is a pan-PPAR agonist." (PMID 35924060, 2022). "The activator of peroxisome proliferator-activated receptor alpha (PPARα) has emerged as a new target for controlling the synthesis and transport of bile acids during cholestasis." (PMID 35924060, 2022). "The PPARα agonist Wy-14643 attenuated ANIT-induced cholestasis and liver injury, coincident with the inhibition of JNK signalling." (PMID 35370715, 2022). "In this study, we aimed to identify the effects of MBT1805, a novel balanced PPARα/γ/δ agonist, on cholestasis induced by α-naphthylisothiocyanate (ANIT) and elucidate the underlying mechanisms through untargeted and bile acid-targeted metabolomic analysis." (PMID 34776958, 2021). "PPARα and PPARγ have been reported to have protective effects in cholestasis by regulating bile acid metabolism in hepatocytes." (PMID 34776958, 2021). "In conclusion, this present study demonstrated the protective role of PPARα signaling activated by fenofibrate in ANIT-induced cholestasis." (PMID 28855630, 2017). "This study aims to evaluate the effect of PPARα agonists, fenofibrate, bezafibrate, and gemfibrozil, on acute cholestasis induced by ethinylestradiol (EE) plus chlorpromazine (CPZ) in rats." (PMID 23997763, 2013). "So, further clinical studies are recommended to investigate fibrate efficacy on cholestasis due to the difference in PPARα expression between animals and human." (PMID 23997763, 2013). "The effects of PPARα on biliary phospholipid secretion, BA metabolism, and synthesis make PPARα an interesting therapeutic target in the treatment of cholestasis." (PMID 23540496, 2013). "Being commercially available drugs makes studies on fibrates (known as being PPARα agonists) for cholestasis management with higher priority than potent FXR ligands under early clinical trials." (PMID 23997763, 2013). "This study aims to evaluate the effect of short-term administration of fenofibrate, a PPARα agonist, on proinflammatory cytokines, apoptosis, and hepatocellular damage in cholestasis." (PMID 18045488, 2007).